PRTN3 (proteinase 3)
Diseases named in the same sentence as PRTN3 in open-access papers (continued):
Sharing a sentence is not in itself a finding about the gene and the disease.
granulomatosis with polyangiitis (215 papers, 2001 to 2026). A small-vessel necrotizing vasculitis characterized by the association of inflammation of the vessel wall and peri- and extravascular granulomatosis. "Granulomatosis with polyangiitis (GPA) is a systemic small-vessel vasculitis typically associated with anti-proteinase-3 antibodies." (PMID 41798537, 2026). "C-ANCA targeting proteinase-3 (PR3) has been associated with granulomatosis with polyangiitis (GPA), whereas P-ANCA targeting MPO is associated with microscopic polyangiitis (MPA)." (PMID 34440897, 2021). "Granulomatosis with polyangiitis (GPA) is a severe autoimmune vasculitis associated with the presence of anti-neutrophil cytoplasmic antibodies (ANCA) mainly targeting proteinase 3 (PR3), a neutrophilic serine proteinase." (PMID 33101296, 2020). "Proteinase 3 (PR3) is the autoantigen in granulomatosis with polyangiitis, an autoimmune necrotizing vasculitis associated with anti-neutrophil cytoplasmic antibodies (ANCAs)." (PMID 29755460, 2018). "The proteinase 3 (PR3)-positive anti-neutrophil cytoplasmic autoantibody (ANCA)-associated vasculitis (AAV) granulomatosis with polyangiitis (GPA) has been associated with chronic nasal S. aureus carriage, which is a risk factor for disease relapse." (PMID 28939882, 2017). "The c-ANCA associated with Wegener's Granulomatosis is almost always an anti PR3(Proteinase 3) antibody." (PMID 21264088, 2008). "Anti-MPO antibodies are characteristic in CSS (associated with p-ANCA), whereas anti-proteinase 3 (PR3) are more specific for Wegener granulomatosis (associated with c-ANCA)." (PMID 23283308, 2008). "Granulomatosis with polyangiitis has a strong association with antineutrophil cytoplasmic antibodies (ANCAs) which characteristically have a cytoplasmic labeling pattern (C-ANCA) in immunofluorescence assays directed against proteinase-3 and myeloperoxidase." (PMID 26664797, 2015). "GPA is typically associated with proteinase 3 (PR3) epitopes, while other entities like microscopic polyangiitis (MPA) and eosinophilic granulomatosis with polyangiitis (EGPA) are linked to myeloperoxidase (MPO)-ANCA or negative ANCA." (PMID 40095487, 2025). "This is somewhat older than proteinase-3 (PR3)-ANCA-positive granulomatosis with polyangiitis (GPA), which is more common in Northern Europe, Australia, and the United States." (PMID 41408511, 2025). "Later, a positive anti-proteinase 3 antibody test and a CT chest scan showing bilateral ground glass opacities confirmed granulomatosis with polyangiitis (GPA)." (PMID 39640133, 2024). "Six of the nine patients were granulomatosis with polyangiitis (GPA) proteinase 3 (PR3)-ANCA positive." (PMID 38833076, 2024). "Proteinase 3 antineutrophil cytoplasmic antibody (PR3-ANCA) is a serologic marker for granulomatosis with polyangiitis." (PMID 37761298, 2023). "Granulomatosis with polyangiitis is a chronic systemic inflammation of small vessels characterized by circulating anti-proteinase 3 antibodies." (PMID 35380163, 2022). "A ~ 60-year-old patient presented for investigation of acute kidney injury, epistaxis and high proteinase 3 (PR3) antibody, on a background of known granulomatosis with polyangiitis (GPA)." (PMID 33856685, 2021). "It has been reported that antibodies against proteinase 3 (PR3) are present in the sera of patients with Wegener's granulomatosis 24,57." (PMID 33746569, 2021). "Braun Braun MG MG Proteinase 3, the target antigen of anticytoplasmic antibodies circulating in Wegener’s granulomatosis." (PMID 32725492, 2020). "Immunolocalization in normal and pathologic tissues Proteinase 3, the target antigen of anticytoplasmic antibodies circulating in Wegener’s granulomatosis." (PMID 32725492, 2020). "Proteinase 3 (PR3), which is mainly produced by neutrophils and is the main autoantigen in granulomatosis with polyangiitis, binds also to endothelium and induces CXCL8 (IL-8) and CCL2 (MCP-1) that provide chemotactic signals for neutrophils and monocytes." (PMID 28018358, 2016).
granulomatosis with polyangiitis (continued). "Granulomatosis with polyangiitis (GPA), formerly called Wegener’s Granulomatosis, generally presents with pulmonary and renal failure due to vasculitis caused by antineutrophil cytoplasmic antibodies directed against cytosolic proteinase-3 (cANCA)." (PMID 24495297, 2014). "A diagnosis of Wegener’s granulomatosis was confirmed by the results of the serologic antibody tests: her c-ANCA titer was considerably elevated at 1:2560 specific for subclass proteinase 3 (PR3) (>200kU/L)." (PMID 23718545, 2013). "In contrast, autoantibodies to proteinase 3 (PR3) are extremely useful as a diagnostic and disease activity indicator in granulomatosis with polyangiitis (GPA)." (PMID 23253567, 2012). "MAbs 3D4 and 0211 were also examined for binding to Sm, lipopolysaccharide (LPS), BSA, and proteinase -3 (PR-3) which is the target autoantigen in Wegener's granulomatosis." (PMID 21245919, 2011). "Proteinase-3 has been identified as the major target-autoantigen of c-ANCA in cases with Wegener's granulomatosis, while myeloperoxidase is the documented autoantigen of p-ANCA in most patients with microscopic polyangiitis." (PMID 15679907, 2004). "ANCA and, more specifically, the enzymes myeloperoxidase (MPO) and proteinase 3 (PR3) are found in autoimmune vasculitis, which is known as ANCA-associated vasculitis and includes granulomatosis with polyangiitis, microscopic polyangiitis, and eosinophilic granulomatosis." (PMID 38283493, 2023). "Granulomatosis with polyangiitis (GPA) is a chronic systemic necrotizing granulomatous vasculitis, which is classified as a small vessel inflammation associated with antineutrophil cytoplasmic antibodies (ANCAs) that target proteinase 3 (PR3 or cANCA)." (PMID 37626497, 2023). "Granulomatosis with polyangiitis (GPA) is a necrotizing granulomatous vasculitis of medium- and small-caliber vessels associated with the presence of antineutrophil cytoplasm antibodies (ANCAs) and antibodies specific for proteinase 3 (anti-PR3)." (PMID 35755572, 2022). "Granulomatosis with polyangiitis, formerly known as Wegener’s granulomatosis, is also an ANCA-associated primary systemic vasculitis (usually against proteinase 3: c-ANCA) of the small-to-medium sized vessels that primarily affects the upper and lower respiratory tract as well as renal glomeruli." (PMID 33935704, 2021). "The following search terms were used alone or in various combinations: “ANCA,” “proteinase 3/PR3-ANCA,” “myeloperoxidase/MPO-ANCA,” “ANCA-associated vasculitis,” “Wegener's granulomatosis,” “microscopic polyangiitis,” “Central nervous system,” “brain” and “spinal cord”." (PMID 30687221, 2018). "In addition, it is well known that the autoantibodies against proteinase 3 (PR3) acted as an obligate feature in developing systemic autoimmune vasculitis such as Wegener's granulomatosis." (PMID 30159339, 2018). "Granulomatosis with polyangiitis (GPA, previously known as Wegener’s granulomatosis) describes systemic vasculitis of small vessels that is strongly associated with antineutrophil cytoplasmic antibodies (ANCAs) directed against proteinase-3." (PMID 29319717, 2017). "A diagnosis of Wegener’s granulomatosis was confirmed by the results of serologic antibody tests: her cytoplasmic antineutrophil cytoplasmic antibody titer was considerably elevated at 1:2560 specific for subclass proteinase 3 (>200kU/L)." (PMID 23718545, 2013). "Wegener's Granulomatosis is a systemic small vessel vasculitis of unknown etiology, associated with the presence of anti-neutrophil cytoplasmic antibodies ANCA usually C-ANCA directed against Proteinase 3 (PR-3)." (PMID 18673582, 2008). "He had been diagnosed with granulomatosis with polyangiitis (GPA) at the age of 34, presenting with skin rash, left-side joint pains, and a positive antibody to Proteinase 3 (PR3)." (PMID 40327197, 2025). "The antiproteinase-3 (C-ANCA) marker is highly sensitive and specific for diagnosing granulomatosis with polyangiitis, GPA." (PMID 39224588, 2024).
granulomatosis with polyangiitis (continued). "We report a case of a 21-year-old male with HIV who presented with persistent fever and was found to have a positive proteinase-3 antibody, raising suspicion of granulomatosis with polyangiitis (GPA)." (PMID 38143617, 2023). "Granulomatosis with polyangiitis (GPA) and microscopic polyangiitis (MPA) are autoimmune vasculitides associated with antineutrophil cytoplasm antibodies that target proteinase 3 (PR3) or myeloperoxidase (MPO) found within neutrophils and monocytes." (PMID 36801813, 2023). "The majority of patients with the clinical syndrome of granulomatosis with polyangiitis (GPA) have ANCA to proteinase 3 (PR3), whereas most patients with microscopic polyangiitis (MPA) have ANCA directed against myeloperoxidase (MPO)." (PMID 36125911, 2022). "Small vessel vasculitides, such as granulomatosis with polyangiitis (GPA) and microscopic polyangiitis (MPA), are strongly associated with ANCA, which are either directed to myeloperoxidase (MPO) or proteinase 3 (PR3)." (PMID 28084533, 2017). "Granulomatosis with polyangiitis is a life-threatening systemic vasculitis, characterised by anti-neutrophil cytoplasmic autoantibodies (ANCA) most commonly against proteinase 3 (PR3), a protease expressed intracellularly and on the surface of neutrophils." (PMID 41703070, 2026). "Granulomatosis with polyangiitis (GPA) and microscopic polyangiitis (MPA) are systemic small-vessel vasculitides, often associated with positive antineutrophil cytoplasmic antibodies (ANCA) targeting either proteinase 3 (PR3) or myeloperoxidase (MPO)." (PMID 40539188, 2025). "AAV is divided into three distinct clinical-pathological phenotypes including granulomatosis with polyangiitis (GPA), microscopic polyangiitis (MPA) and eosinophilic granulomatosis with polyangiitis (EGPA), and are associated with proteinase 3 (PR3) and myeloperoxidase (MPO) antibodies." (PMID 40907826, 2025). "Interesting findings have been associated with proteinase 3 antineutrophil cytoplasmic antibody (PR3-ANCA), mostly known as a marker for granulomatosis with polyangiitis." (PMID 39062093, 2024). "Previous studies suggested that monocytes upregulate major histocompatibility complex (MHC) II cell surface receptor human leukocyte antigen receptor (HLA-DR) molecules in granulomatosis with polyangiitis (GPA) patients with proteinase 3 (PR3)- and myeloperoxidase (MPO)-ANCA seropositivity." (PMID 35632410, 2022). "Granulomatosis with polyangiitis (GPA) is a systemic, necrotizing vasculitis mediated by antineutrophil cytoplasmic antibodies (ANCA) against proteinase 3 (PR3)." (PMID 36326380, 2022). "Eosinophilic granulomatosis with polyangiitis (EGPA), Granulomatosis with polyangiitis (GPA), and microscopic polyangiitis (MPA), are the major categories of AAV, and proteinase 3 (PR3) and myeloperoxidase (MPO) are two major antigens of ANCA2." (PMID 33664381, 2021). "That is, whether classification should be based on the serotype (proteinase 3 (PR3)- or myeloperoxidase (MPO)-ANCA) or on the clinical phenotype (granulomatosis with polyangiitis (GPA) or microscopic polyangiitis (MPA))." (PMID 33909191, 2021). "Furthermore, the pathogenesis of ANCA-associated vasculitis has been reviewed with particular emphasis on the role of proteinase 3 (PR3) in fuelling granulomatosis with polyangiitis (GPA) inflammation." (PMID 31198793, 2019). "Granulomatosis with polyangiitis (GPA) is a systemic inflammatory, prototype autoimmune disease characterized by the presence of anti-proteinase-3 autoantibodies." (PMID 27624647, 2016). "C-ANCA (IIF), proteinase-3 (PR3)-ANCA (ELISA), and myeloperoxidase (MPO)-ANCA (ELISA) in granulomatosis with polyangiitis (GPA), and MPO-ANCA (ELISA) in propylthiouracil-induced vasculitis were IgG1/4-dominant." (PMID 26018403, 2015). "In Wegener's granulomatosis (WG), a prototype AAV, ANCA are mainly directed against proteinase 3 (PR3)." (PMID 21437233, 2011).
granulomatosis with polyangiitis (continued). "Anti-neutrophil cytoplasmic autoantibodies (ANCA) are found in primary vasculitic syndromes, granulomatosis and polyangiitis (GPA) and microscopic polyangiitis (MPA) exhibit specificity for azurophilic granular proteins proteinase 3 (PR3) and myeloperoxidase (MPO)." (PMID 34142075, 2021). "Microscopic polyangiitis (MPA) and myeloperoxidase (MPO)-ANCA positive AAV (MPO-AAV) are predominant in East Asian populations, while granulomatosis with polyangiitis (GPA) and proteinase 3 (PR3)-ANCA positive AAV (PR3-AAV) are common in the populations of European ancestry." (PMID 33076992, 2020). "Typically, c-ANCA targets proteinase 3 (PR3) and is predominant in granulomatosis with polyangiitis (GPA), while p-ANCA targets myeloperoxidase (MPO) and is more common in microscopic polyangiitis (MPA), though these associations are not absolute." (PMID 39456878, 2024). "This is a retrospective cohort study on myeloperoxidase (MPO)-ANCA or proteinase 3 (PR3)-ANCA positive patients with AAV (microscopic polyangiitis, MPA; or granulomatosis with polyangiitis, GPA) and eGFR <15 ml/min per 1.73 m2 or ESKD at presentation." (PMID 38707835, 2024). "Granulomatosis with polyangiitis (GPA) is characterized by chronic necrotizing granulomatous inflammation with a predilection of the upper and lower respiratory tract and proteinase 3 (PR3) specific cytoplasmic anti-neutrophil cytoplasmatic antibodies (C-ANCA)." (PMID 23031229, 2012). "This multicentre, retrospective cohort study analysed data from a nationwide Japanese registry of 729 newly diagnosed patients with granulomatosis with polyangiitis (GPA) or microscopic polyangiitis (MPA), all positive for myeloperoxidase (MPO)- or proteinase 3 (PR3)-ANCA." (PMID 41222744, 2025). "Systemic small vessel vasculitis with renal involvement is mostly associated with an anti-neutrophil cytoplasmic antibody (ANCA) directed at leukocyte proteinase 3 (PR3-ANCA) and myeloperoxidase (MPO-ANCA), including MPA, GPA, and eosinophilic granulomatosis with polyangiitis (Churg–Strauss)." (PMID 38248794, 2024). "AAV includes microscopic polyangiitis (MPA), granulomatosis with polyangiitis (GPA), eosinophilic granulomatosis with polyangiitis (EGPA), renal-limited AAV, and certain drug-induced vasculitis syndromes which may be ANCA specific for either myeloperoxidase (MPO-ANCA) or proteinase 3 (PR3-ANCA)." (PMID 35759125, 2022). "Evidence is lacking for direct pathogenicity of human anti-proteinase-3 (PR3) antibodies in development of systemic vasculitis and granulomatosis with polyangiitis (GPA, Wegener's granulomatosis)." (PMID 22247758, 2012).
microscopic polyangiitis (104 papers, 2001 to 2026). Microscopic polyangiitis (MPA) is an inflammatory, necrotizing, systemic vasculitis that affects predominantly small vessels (i.e. small arteries, arterioles, capillaries, venules) in multiple organs. "The available evidence suggests an increased risk of granulomatosis with polyangiitis and proteinase 3 antibody positivity with increasing latitude and decreased UV exposure, with an inverse relationship for microscopic polyangiitis and myeloperoxidase antibody positivity." (PMID 37675201, 2023). "Microscopic polyangiitis is associated with proteinase 3 (PR3)-ANCA in 26% of cases and with myeloperoxidase (MPO)-ANCA in 58% of cases, while GPA is characterized by PR3-ANCA in 66% of patients and MPO-ANCA in 24% of patients." (PMID 25452756, 2014). "Granulomatosis with polyangiitis typically displays a pattern of cytoplasmic ANCA (C-ANCA) almost exclusively as a result of antibodies directed against proteinase-3 (PR3), while microscopic polyangiitis typically shows a pattern of perinuclear ANCA (P-ANCA) targeting myeloperoxidase." (PMID 37375793, 2023). "The systemic autoimmune diseases granulomatosis with polyangiitis and microscopic polyangiitis are small vessel vasculitis syndromes associated with circulating antineutrophil cytoplasmic antibodies (ANCA), which target either proteinase 3 (PR3) or myeloperoxidase (MPO)." (PMID 34618687, 2021). "In real clinical practice, patients classified as microscopic polyangiitis (MPA) according to the new 2022 criteria, despite proteinase 3 (PR3)-antineutrophil cytoplasmic antibody (ANCA) positivity, are occasionally encountered." (PMID 41601767, 2026). "Anti-proteinase 3 activity (PR3-ANCA) is most common in GPA, while patients with microscopic polyangiitis and Churg–Strauss syndrome are most often anti-myeloperoxidase ANCA (MPO-ANCA) positive." (PMID 35897050, 2022). "Antineutrophil cytoplasmic antibodies (ANCA) specific for proteinase 3 (PR3) and myeloperoxidase (MPO) are associated with necrotizing vasculitides, especially Wegener's granulomatosis (WG), microscopic polyangiitis (MPA) and idiopathic crescentic glomerulonephritis." (PMID 16207324, 2005). "Microscopic polyangiitis (MPA) is a type of AAV marked by renal involvement, which often leads to rapidly progressive glomerulonephritis and the presence of myeloperoxidase-ANCA (MPO-ANCA; although proteinase 3 (PR3)-ANCA has also been reported)." (PMID 36938279, 2023). "Although c-ANCA (with proteinase 3 specificity) mostly appear in Wegener’s granulomatosis (80-90% of ANCA-positive GPA patients), and p-ANCA (directed against myeloperoxidase) are mainly found in microscopic polyangiitis, 10-20% of ANCA-positive GPA patients have increased p-ANCA levels." (PMID 33817443, 2021). "Eight years before presentation at our hospital, at age 63, she was clinically diagnosed with microscopic polyangiitis (MPA) based on rapidly progressive glomerulonephritis, mononeuropathy multiplex, positive MPO-ANCA, and negative proteinase 3–ANCA; no renal biopsy was conducted at that time." (PMID 40750159, 2025).